FGF10 (fibroblast growth factor 10)
Diseases named in the same sentence as FGF10 in open-access papers (continued):
Sharing a sentence is not in itself a finding about the gene and the disease.
ameloblastoma (4 papers, 2013 to 2024). The most common odontogenic tumor, arising from the epithelial component of the embryonic tooth and usually affecting the molar-ramus region of the mandible or maxilla. "By western blot analyses, FGF7 and FGF10 were also detected in the ameloblastoma tissues and AM-1 cells." (PMID 24002438, 2013). "In conclusion, this study showed that FGF7 and FGF10 are expressed in ameloblastomas and that they play an important role in the growth of ameloblastomas through the MAPK pathway." (PMID 24002438, 2013). "Next, we performed immunohistochemistry to analyze the expression of FGFR1 and FGFR2, the specific receptors of FGF7 and FGF10, in the ameloblastoma specimens and in AM-1 cells." (PMID 24002438, 2013). "Cabe resaltar que la mayor expresión de los ligandos FGF-7 y FGF-10 tuvo una mayor expresión en células estromales, lo que podría indicar que estos actúan como agentes paracrinos en la proliferación del ameloblastoma." (PMID 39444727, 2024). "Moreover, increased expression of FGF10 along with FGF7 was found in samples from human ameloblastoma, a benign jaw tumor originating from the cells of odontogenic epithelium, and FGF10 was shown to directly support proliferation of these cells." (PMID 30505318, 2018). "Taken together, FGF7 and FGF10 may play important roles in the proliferation and progression of ameloblastoma." (PMID 24002438, 2013). "Therefore, to examine the effects of FGF7 and FGF10 on the proliferation of ameloblastoma, cell proliferation assays were performed." (PMID 24002438, 2013). "In the present study, we thus hypothesized that FGF3, FGF7 and FGF10 may also affect the proliferation of ameloblastoma cells with odontogenic epithelial characteristics and show some evidences that FGF signaling involved in the ameloblastoma proliferation through MAPK pathway." (PMID 24002438, 2013). "In this study, we examined the expression of FGF3, FGF7, FGF10 and their specific receptors in histologically various types of ameloblastoma and analyzed the effect of these growth factors on the proliferation of ameloblastoma using the ameloblastoma cell line AM-1." (PMID 24002438, 2013). "We examined 32 cases of ameloblastoma as well as AM-1 cells (an ameloblastoma cell line) and studied the expression of FGF3, FGF7, FGF10 and their specific receptors, namely, FGF receptor (FGFR) 1 and FGFR2." (PMID 24002438, 2013). "The expression of FGF7, FGF10, FGFR1 and FGFR2 was detected in ameloblastoma cells and AM-1 cells, while that of FGF3 was not." (PMID 24002438, 2013).
Cerebral ischemia (4 papers, 2016 to 2020). Restriction of arterial blood supply to the brain associated with insufficient oxygenation to support the metabolic requirements of the tissue. "Recent studies have reported the protective effect of FGF10 on spinal cord injury, cerebral ischemia injury and acute lung injury via inhibiting inflammation, activating PI3K/AKT signaling pathway or mobilization of stem cells." (PMID 30532765, 2018). "Previous studies have shown that neuron-derived FGF10 exerts potential neuroprotective effects after cerebral ischemia injury." (PMID 28981091, 2017). "In conclusion, we demonstrate that neuron-derived FGF10 ameliorates cerebral ischemia injury via inhibiting NF-κB-dependent neuroinflammation and activating PI3K/Akt survival signaling pathway in mice." (PMID 26813160, 2016). "Collectively, our results demonstrate that neuron-derived FGF10 ameliorates cerebral ischemia injury via inhibiting NF-κB-dependent neuroinflammation and activating PI3K/Akt survival signaling pathway in mice." (PMID 26813160, 2016). "In the present study, we provide the first evidence that neuron-derived FGF10 ameliorates cerebral ischemia injury in vivo." (PMID 26813160, 2016). "Next, we tested the influence of experimental cerebral ischemia on FGF10 mRNA and protein expression." (PMID 26813160, 2016). "In view of that our previous results have revealed the potential neuroprotection of FGF10 in cultured neuron model (in vitro), we considered that the upregulated brain FGF10 level by cerebral ischemia might affect the outcome of ischemic stroke in vivo." (PMID 26813160, 2016). "Since brain FGF10 is upregulated by cerebral ischemia, we proposed that the upregulated FGF10 might have important physiopathological roles during cerebral ischemia." (PMID 26813160, 2016). "Fibroblast growth factor 10 (FGF10), a multifunctional FGF family member, was reported to exert protective effect against cerebral ischemia injury and myocardial damage." (PMID 30532765, 2018). "Two recent studies suggested that neuron and microglia or macrophage-derived FGF10 participates in activation of PI3K/AKT/mTOR, which contributes to either ameliorate cerebral ischemia injury or improve functional recovery after spinal cord injury." (PMID 30532765, 2018). "Our data indicate that intracranial FGF10 administration protected experimental ischemic stroke via activating PI3K/Akt pathway and suppressing neuroinflammation triggered by cerebral ischemia." (PMID 26813160, 2016).
cleft palate (4 papers, 2017 to 2025). Cleft palate is a fissure type embryopathy that affects the soft and hard palate to varying degrees. "Fgf8 overexpression in mice results in cleft palate, while Fgf10, a loss of which also results in cleft palate, seems to function in cooperation with Wnt signaling." (PMID 30760477, 2019). "Previous studies showed that deletion of Osr2, Fgf10, and Shh all lead to cleft palate during normal palatal development, and they play an important role in the regulation of palatal protrusive cell proliferation." (PMID 40429955, 2025). "FGF signaling is known to play a role in palate fusion, as Fgf10 and Fgfr2b knockout mice exhibit cleft palate, likely due to reduced mesenchymal proliferation and associated failure of palatal elevation and outgrowth." (PMID 28898253, 2017).
emphysema (4 papers, 2014 to 2025). "We used the murine emphysema model and in vitro studies to determine the protective and reparative role of FGF10/FGFR1." (PMID 36183124, 2022). "Pretreatment of FGF10 attenuated the development of emphysema and the shedding of glycocalyx components induced by CSE in vivo." (PMID 36183124, 2022). "Importantly, administration of FGF10 rescued glycocalyx impairment and emphysema in a murine model of COPD, probably through a FGFR1/ERK/SOX9/HS6ST1 loop in endothelial cells." (PMID 36183124, 2022). "Interestingly, Fgf10 haploinsufficiency is linked to emphysema in COPD in humans, which further emphasizes the significance of Fgf10 expression in adult lung stem cell niches and its role in homeostasis and regeneration." (PMID 24891877, 2014). "Surprisingly, FGF10 increased the intensity of HS, CS and syndecan-1 even with a low dose of 10 or 100 μg/kg, while FGF10 attenuated emphysematous changes when the dose escalated to at least 1 mg/kg, indicating that glycocalyx repair is a process prior to repair of emphysema." (PMID 36183124, 2022). "Therefore, further studies are needed to clarify the crosstalk between these receptors, and to explore whether FGF10 attenuates endothelial apoptosis and emphysema through pathways other than FGFR1." (PMID 36183124, 2022). "Here, we demonstrated that intravenous injection of FGF10 has a protective effect on CSE-induced glycocalyx impairment and emphysema in a dose-dependent manner." (PMID 36183124, 2022). "In elastase-induced emphysema model, both wildtype and STAB2 variants of FGF10 increased cell proliferation with no impact on metabolic activity." (PMID 40257501, 2025). "In contrast, FGF10 with a dose of 1 or 2 mg/kg did not prevent KLAKLAK2-induced emphysema which serves as positive controls." (PMID 36183124, 2022). "Furthermore, since especially the expression of regenerative factors is of relevance with respect to therapeutic effects in emphysema, we performed targeted analysis on growth factors that play a critical role in alveolar epithelial regeneration based on literature, FGF7/KGF, FGF10 and HGF." (PMID 36681830, 2023). "However, 1 mg/kg or 2 mg/kg FGF10 did not alleviate the degree of emphysema." (PMID 36183124, 2022).
endometrial carcinoma (4 papers, 2016 to 2025). A malignant tumor arising from the epithelium that lines the cavity of the uterine body. "In human diseases, FGF10 is capable of stimulating the growth of endometrial carcinoma cells by activating the ERK1/2 pathway in a paracrine manner and is involved in the growth of ameloblastoma – an epithelial benign tumor of the odontogenic apparatus – partially signaling through ERK1/2." (PMID 30405705, 2018). "In 2003, ELK1 was identified as a downstream target of Fibroblast growth factor 7 (FGF7; also known as Keratinocyte growth factor, KGF) and Fibroblast growth factor 10 (FGF10; also known as Keratinocyte growth factor 2, KGF2) in human Endometrial carcinoma (EC) cells." (PMID 40862737, 2025). "ELK-1 and c-MYC, but surprisingly not c-FOS, are regulated by FGF10 in endometrial carcinoma." (PMID 30405705, 2018).
gastric cancer (4 papers, 2018 to 2024). A primary or metastatic malignant neoplasm involving the stomach. "FGF10 amplification has also been detected in 3% of gastric cancers and immunohistochemical analysis of 178 gastric adenocarcinoma samples revealed that FGF10 levels are correlated with poor prognosis." (PMID 30405704, 2018). "CiRS-133 in plasma exosomes obtained from gastric cancer patients stimulated WAT browning by activating PRDM16, and circNrxn2 had the same effect by increasing the expression levels of fibroblast growth factor 10 (FGF10) in mice fed a HFD." (PMID 35445015, 2022).
hepatocellular carcinoma (4 papers, 2012 to 2025). A malignant tumor that arises from hepatocytes. "Multiple FGFs have been found elevated in different kinds of tumours, such as FGF2 in leukaemia, lung and breast cancer, FGF8 in breast and prostate cancer, FGF10 in lung cancer, FGF19 in hepatocellular carcinoma (HCC) and TNBC." (PMID 33655556, 2021). "FGF8 and FGF10 are involved in embryonic liver development, FGF7 and FGF9 in repair in response to liver injury, and FGF5, FGF8, FGF9, FGF17, and FGF18 in the development and progression of hepatocellular carcinoma." (PMID 27148532, 2016).
Hypertension (4 papers, 2020 to 2022). The presence of chronic increased pressure in the systemic arterial system. "Interestingly, rs8109113 in the FGF22 gene was associated with both hypertension and height, and 17 SNPs in FGF10, FGF18, and FGF2 were associated with both osteoporosis and height." (PMID 35980984, 2022). "Similarly, the FGF2, FGF4, FGF10, FGF18, and FGF22 genes, which showed interactions with the FGFRL1 gene, were associated with height, hypertension, and osteoporosis." (PMID 35980984, 2022). "In 2018, Shi found that lncRNA TUG1/miR-145-5p/FGF10 regulated VSMC proliferation and migration of hypertension patients." (PMID 35635088, 2022). "The FGF10, FGF18, FGF2, FGF4, and FGF22 genes, which interact with FGFRL1, were correlated with height, hypertension, and osteoporosis." (PMID 35980984, 2022). "Examples include AK098656, which promotes hypertension through regulation of vascular smooth muscle cells (VSMCs) functions, GAS5, which promotes vascular remodeling and is downregulated in hypertension, and the TUG1/miR-145-5p/FGF10 axis, which regulates proliferation and migration in VSMCs." (PMID 32392180, 2020).
lung adenocarcinoma (4 papers, 2017 to 2022). A carcinoma that arises from the lung and is characterized by the presence of malignant glandular epithelial cells. "Or perhaps it prevents initiation of lung adenocarcinoma, the leading cancer killer, when an AT2 cell divides and a daughter loses contact with the underlying stromal cells that express the Fgf7 and Fgf10 survival signals." (PMID 36414616, 2022). "FGF9 activates FGFR3 in the respiratory epithelium both during organogenesis and development of lung adenocarcinoma, whereas FGF7 and FGF10 signal through FGFR2b in the airway epithelium." (PMID 35675358, 2022).
Obesity (4 papers, 2018 to 2026). Accumulation of substantial excess body fat. "Fgf10 has also been proposed as a candidate for novel anti-obesity drugs and our rat model may be useful to investigate its potential therapeutic efficacy." (PMID 34065591, 2021). "More recently, it has been suggested that the miR-327/FGF10/FGFR2 signaling axis may be a therapeutic target for treatment of obesity and metabolic diseases and that the crosstalk between miR-145-5p and FGF10 expression regulates vascular smooth muscle cells proliferation and migration." (PMID 30405705, 2018).
psoriasis (4 papers, 2015 to 2021). An autoimmune condition characterized by red, well-delineated plaques with silvery scales that are usually on the extensor surfaces and scalp. "Psoriasis is characterized by the presence of a lymphocyte infiltrate that correlates with the level of Fgf10 expression." (PMID 34136479, 2021). "In another, anti-FGF10 monoclonal antibody inhibited proliferation of human keratinocytes and reduced inflammation in propranolol-induced psoriasis-like lesions." (PMID 34383782, 2021). "While the downstream effects on TNF-α and IL-10 have already been indicated as key components of this pathway, there also appears to be a role for fibroblast growth factor 10 (FGF10) in determining the influence of the SNS on psoriasis." (PMID 26550011, 2015). "This reaffirmed that FGF10 exerts an effect on psoriasis severity and that disruption of normal β-AR activity—as observed in chronic diseases like rheumatoid arthritis or psoriasis—can allow for this effect to rise above the normal anti-inflammatory actions, otherwise keeping it in check." (PMID 26550011, 2015). "Therefore, our findings may provide proof of principle that blockage of FGF10 can inhibit psoriasis-related inflammation." (PMID 34383782, 2021).
Apert syndrome (3 papers, 2009 to 2018). Apert syndrome (AS) is a frequent form of acrocephalosyndactyly, a group of inherited congenital malformation disorders, characterized by craniosynostosis, midface hypoplasia, and finger and toe anomalies and/or syndactyly. "Fgf10 mRNA is present in the osteoprogenitors in the frontal bone condensation, and genetic knock-down of Fgf10 rescues the skeletal phenotype in an Apert syndrome mouse model FgfR2-IIIc+/Δ." (PMID 30505318, 2018). "We observed increased expression of Fgf10, Esrp1, and Fgfr2IIIb, which are indispensable for epidermal development, in coronal sutures in Apert syndrome mice." (PMID 25003957, 2014). "Taken together these data suggest that the mutations associated with Apert syndrome affect affinity for the mesodermally expressed by FGF7 and FGF10, resulting in autocrine signaling." (PMID 20108486, 2009). "Interestingly, the FGFR2c linker domain mutations of Apert syndrome result in enhanced binding of FGF7 and FGF10, both mesenchymally expressed ligands of the FGFR2b isoform and important in limb development." (PMID 20108486, 2009).
cleft lip (3 papers, 2018 to 2022). Congenital defect in the upper lip where the maxillary prominence fails to merge with the merged medial nasal prominences. "In humans, genome-wide association studies (GWAS) have shown that SNPs near FGF10 are highly associated with cleft lip and/or palate." (PMID 30505318, 2018). "Taken together, the data from GWAS along with the data from susceptible mouse strains suggest a role for FGF10 in lip development, despite the absence of cleft lip in Fgf10-/- mice." (PMID 30505318, 2018).
congenital heart disease (3 papers, 2019 to 2025). A heart disease that is present at birth. "Research on cardiovascular disease has shown that FGF10 is essential for the development of the myocardium, and the absence or expression of FGF10 can lead to the occurrence of congenital heart disease." (PMID 41239804, 2025). "Although FGF22 was reported most in the neurology, we detected its variant in our patient populations with heart defects and speculated that FGF22 may have some similar function with FGF10 in heart development." (PMID 30745907, 2019).
ischemia (3 papers, 2016 to 2021). A hypoperfusion of the BLOOD through an organ or tissue caused by a PATHOLOGIC CONSTRICTION or obstruction of its BLOOD VESSELS, or an absence of BLOOD CIRCULATION. "FGF10 mRNA level in brain penumbra area of MCAO mice was significantly higher than that in non-ischemia brain area." (PMID 26813160, 2016).
ovarian carcinoma (3 papers, 2021 to 2025). A malignant neoplasm originating from the surface ovarian epithelium. "One study identified the fibroblast growth factor receptor 2 (FGFR2), the receptor for FGF10, as a target of miR-628-5p in ovarian cancer cells." (PMID 33807742, 2021). "Furthermore, FGF10 up-regulation can be used as a biomarker to predict the survival of patients with ovarian epithelial cancer." (PMID 38274662, 2023).
pulmonary adenomas (3 papers, 2016 to 2020). "Whilst FGF10 is crucial for branching morphogenesis in the developing lung, induction of FGF10 over-expression in the respiratory epithelial cells of adult mice has been shown to cause multifocal pulmonary adenomas." (PMID 30405704, 2018).
acute respiratory distress syndrome (2 papers, 2020 to 2022). Progressive and life-threatening pulmonary distress in the absence of an underlying pulmonary condition, usually following major trauma or surgery. "In the adult lung, increased expression of FGF2, FGF7, and FGF10 promotes repair after lung injury, and FGF10 also promotes resolution of acute lung injury and acute respiratory distress syndrome." (PMID 35675358, 2022). "In addition, it has been shown that FGF10 prevents lung injury and promotes lung epithelial regeneration after various stresses, including influenza-induced acute respiratory distress syndrome, lipopolysaccharide-induced lung injury, and mechanical ventilation-induced lung injury." (PMID 31958320, 2020).
alopecia (2 papers, 2015 to 2025). Hair loss usually from the scalp. "Nevertheless, the effect of FGF-1, FGF-2, and FGF-10 in the therapy of hair loss is confirmative and feasible." (PMID 25685806, 2015). "Although arachidonic acid (20:4n-6) stimulates human hair growth via FGF10 upregulation, n-3 PUFAs like DPA (22:5n-3) induce murine alopecia through macrophage-mediated inflammatory cascades." (PMID 41257555, 2025).
anorectal malformation (2 papers, 2023 to 2024). "According to these results, it is suggested that the AR and the Fgf10/Fgfr2 signaling pathways could be involved in the development of anorectal malformations in male rats exposed to DBP in utero." (PMID 39728417, 2024).
asthma (2 papers, 2014 to 2023). "Interestingly, the Wnt pathway is induced in ASMCs in a mouse model for asthma, whereas epithelial Fgf10, as well as downstream Notch signaling, has been shown to be implicated in mucous/goblet cell hyperplasia." (PMID 24891877, 2014). "Thus, chronic activation of Wnt-Fgf10 epithelial-mesenchymal crosstalk is likely involved in ASMC proliferation and airway remodeling observed in asthma patients." (PMID 24891877, 2014).
bladder cancer (2 papers, 2012 to 2020). "Knockdown of FGF10 expression in the bladder cancer cells abrogated the induction of urothelium differentiation in AFSCs." (PMID 32178321, 2020). "A rat bladder carcinoma cell line, NBT-II, can undergo EMT following addition of several growth factors including FGF1, FGF7, and FGF10 and NBT-II carcinoma cell lines that were rendered autocrine for FGF1 activation had a much higher level of tumorigenicity." (PMID 22701738, 2012).